LGALS3 (galectin 3)
Diseases named in the same sentence as LGALS3 in open-access papers (continued):
Sharing a sentence is not in itself a finding about the gene and the disease.
preeclampsia (continued). "Our study revealed reduced placental galectin-3 in established early-onset preeclampsia (delivered at <34 weeks’ gestation)." (PMID 36311252, 2022). "Galectin-3 protein was significantly decreased in placenta from pregnancies (p = 0.002) complicated by preeclampsia (n = 43) compared to gestation matched controls (n = 21)." (PMID 36311252, 2022). "This study showed a reduction of galectin-3 in placenta from pregnancies complicated by early-onset preeclampsia." (PMID 36311252, 2022). "mRNA expression of LGALS3 was significantly reduced (p = 0.009) in placentas from women with preeclampsia (n = 29) compared to controls (n = 18)." (PMID 36311252, 2022). "Therefore, we conduct a narrative review of the literature to investigate and enlighten the possible correlation between galectin-3 and pregnancy pathologies such as gestational hypertension and preeclampsia." (PMID 39200778, 2024). "The potential mechanisms by which galectin-3 may contribute to the development of preeclampsia are multifaceted and involve its role in various cellular processes, including inflammation, angiogenesis, and trophoblast function." (PMID 39200778, 2024). "Galectin-3 has been shown to play a role in various cellular processes, including inflammation, angiogenesis, and trophoblast function, all of which are known to be dysregulated in preeclampsia." (PMID 39200778, 2024). "By exploring the specific mechanisms by which galectin-3 may contribute to the pathophysiology of preeclampsia, researchers may be able to identify new therapeutic targets and develop more effective interventions for this condition." (PMID 39200778, 2024). "A weak expression of galectin-3 was found in healthy first-trimester placentas, whereas an elevated level of galectin-3 is correlated with reduced trophoblast invasion and development of pregnancy-related diseases like preeclampsia and HELLP syndrome." (PMID 37998731, 2023). "Additionally, we assessed galectin-3 and galectin-3BP levels in an in vitro model of preeclampsia where differentiated human trophoblast stem cells (hTSCs) were exposed to hypoxia and pro-inflammatory cytokines." (PMID 36311252, 2022). "Therefore, the dysregulated galectin-3 that was observed in early-onset preeclampsia is unlikely a result of hypoxia." (PMID 36311252, 2022). "This study is the first to evaluate circulating galectin-3 in plasma from women with preeclampsia." (PMID 36311252, 2022). "Given inflammation and placental hypoxia play crucial role in pathophysiology of preeclampsia, we examined the effect of pro-inflammatory cytokines (IL-6 and TNFα) and hypoxia on LGALS3 and LGALS3BP mRNA expression in placental cytotrophoblast and syncytiotrophoblast cells." (PMID 36311252, 2022). "Additionally, the use of galectin-3 as a biomarker may aid in the development of targeted therapies for preeclampsia, as it could help to identify specific pathways or mechanisms that contribute to the development of the disease." (PMID 39200778, 2024). "Given that galectin-3 protein and expression levels were dysregulated in preeclamptic placental lysates, we measured circulating galectin-3 in patients with established early-onset disease relative to gestation matched controls and at 36 weeks prior to any potential term preeclampsia diagnosis." (PMID 36311252, 2022). "Therefore, this study aimed to assess galectin-3 mRNA expression and protein levels in placentas and plasma using two well-defined cohorts, including one with confirmed early-onset preeclampsia, and another collected prior to diagnosis of term preeclampsia." (PMID 36311252, 2022). "Four were robust to sensitivity analyses for gestational hypertension (cluster of differentiation 40, eosinophil cationic protein [ECP], galectin 3, N-terminal pro–brain natriuretic peptide [NT-proBNP]), and 2 were robust for preeclampsia (cystatin B, heat shock protein 27 [HSP27])." (PMID 38170504, 2024).
preeclampsia (continued). "This study identified reduced levels of placental galectin-3 in women with early-onset preeclampsia but no changes within the circulation in established early-onset disease or before development of preeclampsia." (PMID 36311252, 2022). "In a separate cohort of samples collected at 36 weeks’ gestation, circulating galectin-3 was not altered in 23 women who later developed preeclampsia, versus 182 who did not." (PMID 36311252, 2022). "Galectin-3 levels were not different in women who later developed preeclampsia (n = 23) versus controls (n = 182)." (PMID 36311252, 2022). "In our established disease cohort, circulating plasma galectin-3 was not altered in women with early-onset preeclampsia." (PMID 36311252, 2022). "Although our study did not detect changes in galectin-3 in plasma from women with preeclampsia, a reason for this may be due to a reduction of galectin-3 production in the placenta, which reduces the amount secreted into the maternal circulation." (PMID 36311252, 2022).
steatosis (16 papers, 2012 to 2025). Increased lipid within the cytoplasm of cells. "After having successfully induced steatosis with a mixture of palmitic and oleic acid, we observed that LGALS3 silencing resulted in lower hepatic neutral fat content." (PMID 40608687, 2025). "In this study, we employed human multilineage 3D spheroids to elucidate the role of LGALS3 in the development of hepatocyte steatosis and fibrosis." (PMID 40608687, 2025). "Consistent with the marked benefits on steatosis and lobular inflammation scores, semaglutide and lanifibranor significantly reduced %-area and total levels of lipids and galectin-3." (PMID 38155202, 2023). "fed both wild-type (LGALS3+/+) and galactin-3 defective (LGALS3-/-) mice an atherogenic diet more than a longer length of time before the levels of fibrosis, inflammation, and steatosis in wild-type mice were much lower than those in wild-type mice." (PMID 36405706, 2022). "Individual reductions in Col1a1 fractional area closely correlated to corresponding improvements in steatosis and galectin-3%-area." (PMID 31227742, 2019). "In a swine model of NASH, the expression of the LGALS3 gene is upregulated during the transition from steatosis to steatohepatitis, and increased expression of LGALS3 may be used in the evaluation of disease progression." (PMID 39125698, 2024). "In particular, as recently reported, SerpinB3 was able to influence the hepatic levels of Galectin 3, CD9 and TREM2, typical markers of NAMs, a population of hepatic macrophages emerging in progressive NAFLD-NASH and strictly associated with severity of steatosis, inflammation as well as fibrosis." (PMID 38307387, 2024). "Having observed induction of steatosis and LGALS3 mRNA levels up-regulation in 3D spheroids following exposure to a mix of palmitic acid and oleic acid, we next investigated whether LGALS3 silencing could influence the neutral lipid content also in this 3D model of steatosis." (PMID 40608687, 2025). "In support of changes in histopathological scores, quantitative markers of steatosis (% area of steatosis) and inflammation (% area of galectin-3) were increased in response to GAN feeding, but not affected by genotype status." (PMID 40604130, 2025).
systemic lupus erythematosus (16 papers, 2011 to 2024). An autoimmune multi-organ disease typically associated with vasculopathy and autoantibody production. "In this study, we provide clinical relevance of galectin-3 to the lupus phenotypes and the underlying mechanisms of galectin-3-mediated NETosis for developing novel therapeutic strategies targeting galectin-3 for SLE." (PMID 37298447, 2023). "Here the authors show that galectin-3 regulates GC development by modulating interferon-γ and B cell-intrinsic signaling, such that galectin-3 deficiency mice exhibit lupus-like autoimmune symptoms." (PMID 29691398, 2018). "Since DAH is an early disease manifestation in pristane-induced lupus mice with the evident pathogenic mechanisms, we plan to determine whether galectin-3 is also involved in this distinct process." (PMID 37298447, 2023). "Interestingly, we found the expression of citH3 was decreased in lung tissue extracts from Gal-3 KO mice when compared with WT mice, suggesting that galectin-3 might be associated with NETosis and exacerbate disease signs in lupus mice." (PMID 37298447, 2023). "We found the galectin-3 stainings were enriched in the immune complex-positive areas of the haemorrhagic lungs from pristane-induced lupus mice." (PMID 37298447, 2023). "A positive correlation between the levels of galectin-3 and SLEDAI-2K was also observed, indicating higher galectin-3 expression correlates with more severe lupus activity." (PMID 37298447, 2023). "Galectin-3 regulates inflammatory reaction in the mesentery during lupus-like responses induced by pristane." (PMID 36353645, 2022). "Galectin-3 is upregulated in several other renal diseases with prominent inflammatory components including systemic lupus erythematosus, experimental glomerulonephritis and unilateral ureteral obstruction." (PMID 21494626, 2011).
acute myeloid leukemia (15 papers, 2017 to 2025). Acute myeloid leukemia (AML) is a group of neoplasms arising from precursor cells committed to the myeloid cell-line differentiation. "Recent studies have shown that LGALS3 is tightly associated with several malignancies such as Hodgkin’s lymphoma, acute myeloid leukemia, and HCC." (PMID 32849813, 2020). "Particularly, it was revealed that Galectin 3 expressed by MSCs in the TME of acute myeloid leukemia (AML) activates MYC expression and contributes to the cell adhesion between MSC and AML tumor, thereby promoting the survival of cancer cells." (PMID 34789315, 2021). "LGALS3 (GALIG) is a novel cell death gene encoding mitogaligin, a protein promoting cytochrome c release upon direct interaction with the mitochondria or nucleus.LGALS3 pro-apoptotic gene is up-regulated during neutrophils apoptosis and under-expressed in acute myeloid leukemia cells." (PMID 28520763, 2017). "While, galectin-3 belongs to another galectin structural group (chimera group with only one CRD) was reported to play an important role in cancerous'-microenvironments, especially in acute myeloid leukemia (AML)." (PMID 36861129, 2023). "Previous studies reported that lymphoid enhancer factor 1 (LEF1) expression and serum Galectin-3 level could affect clinical parameters and outcome in acute myeloid leukemia patients, but as far as we know, no study has addressed their combined effect on AML patients." (PMID 31929803, 2019).
cervical carcinoma (15 papers, 2014 to 2024). A carcinoma arising from either the exocervical squamous epithelium or the endocervical glandular epithelium. "The aim of the present study was the analysis of EP2 as a novel marker and its association to EP3, galectin-3, clinical pathological parameters and the overall survival rate of cervical cancer patients." (PMID 31980713, 2020). "Inconsistent with our results, galectin-3 expression was reported to be down-regulated in cervical cancer tissues and the decreased expression is associated with the progression of cervical neoplasia." (PMID 28355349, 2017). "Because the functions and correlations with clinico-pathological parameters and survival of galectin-3 are so diverse, it will be challenging to use this galectin type as a prognostic or diagnostic marker in cervical cancer." (PMID 26066796, 2015). "In conclusion, this study showed that the expressions of ezrin and galectin-3 protein may be associated with the development of cervical cancer and their overexpressions may indicate a poor prognosis of this disease." (PMID 28355349, 2017). "The aim of this study was to analyze EP2 expression in human squamous cell carcinoma (SCC) and adenocarcinoma (AC) of the cervix in relation to overall survival and to investigate whether EP2 is associated with EP3 and galectin-3 regarding the survival of cervical cancer patients." (PMID 31980713, 2020). "Additional research data reveals a new understanding of how bergenin inhibits the growth of blood vessels in cervical carcinoma cells by affecting various proteins involved in blood vessel formation, such as Galectin-3 and MMP-9." (PMID 39834829, 2024). "It has also been proposed that Galectin-3, by acting as a soluble inhibitory ligand to the activating NK cell receptor NKp30, results in reduced NK cell cytotoxicity towards cervical cancer cells." (PMID 39759523, 2024). "This study for the first time provides deep insight into bergenin-mediated toxicity in cervical carcinoma cells and identifies and validates the potential targets of bergenin, especially Galectin 3 and MMP-9 along with proposing many new ones." (PMID 38961106, 2024). "A significant reduction in protein expression levels of Galectin-3 was observed in bergenin-treated cervical carcinoma cells." (PMID 38961106, 2024). "There are only a few reports concerning the role of galectin-3 in cervical cancer, and literature about the relation between galectin-3 and cervical cancer is limited." (PMID 31980713, 2020). "In culture, down-regulation of galectin-3 in cancer cells promoted NK-mediated tumour cell lysis whilst in subcutaneous murine cervical cancer galectin-3 inhibition sensitised cancer cells to death following adoptive transfer of NK cells." (PMID 33187209, 2020). "Another lectin family member, Galectin-3, is also overexpressed along with Ezrin in cervical cancer and both are predictors of poor prognosis in cervical cancer patients." (PMID 33240887, 2020). "The majority of studies state that EP2 is beneficial for tumor genesis, however, combining EP2 and EP3 or EP2 and galectin-3 showed the converse outcome in cervical cancer." (PMID 31980713, 2020). "A recent study has shown that the overexpression of galectin-3 and ezrin had stronger predictive value than either alone in cervical cancer." (PMID 31832021, 2019). "In this review, we mainly focus on the role of galectins, especially galectin-1, galectin-3, galectin-7, and galectin-9 in cervical cancer, and provide theoretical basis for potential targeted treatment of cervical cancer." (PMID 29854732, 2018). "Spearman analysis showed that ezrin expression was positively correlated with galectin-3 expression in cervical cancer (r=0.355, P<0.05)." (PMID 28355349, 2017). "The mechanisms of ezrin and galectin-3 in the process of development and prognosis for cervical cancer remains to be elucidated, and further research is required." (PMID 28355349, 2017).
cervical carcinoma (continued). "The positive expression rates of ezrin and galectin-3 protein in cervical cancer were significantly higher than cervicitis group, and CIN grade I, II, and III groups (all P<0.05)." (PMID 28355349, 2017). "Ezrin and galectin-3 expressions in cervical cancer were significantly higher than in normal cervix, cervicitis and CIN (all P<0.05), and expressions in CIN were significantly higher than in normal cervix and cervicitis (both P<0.05)." (PMID 28355349, 2017). "Currently, few studies have focused on the expression of ezrin and galectin-3 protein in cervical cancer." (PMID 28355349, 2017). "Ezrin and galectin-3 expressions in cervical cancer scored – and + were grouped into low expression group, while ++ and +++ were grouped into high expression group." (PMID 28355349, 2017). "The expressions of ezrin and galectin-3 were correlated with the development of cervical cancer, and overexpressions of those proteins were indicative of poor prognosis in patients with cervical cancer." (PMID 28355349, 2017). "The survival rate for cervical cancer patients with high expressions of ezrin and galectin-3 was significantly lower than those with low expressions of the proteins (both P<0.05)." (PMID 28355349, 2017). "The aim of this study was to explore the correlation of ezrin and galectin-3 expressions with prognosis in cervical cancer." (PMID 28355349, 2017). "This study also found that galectin-3 protein expression was related with the development and prognosis of cervical cancer." (PMID 28355349, 2017). "Recently, it was shown that VEGF-C provokes the rearrangement of actin filaments in cervical cancer cells and drives cell migration and invasion via upregulation of galectin-3 protein and subsequent VEGFR-3 activation." (PMID 25268128, 2014). "In addition, another study by our research group proved that galectin-3 expression was correlated with poor prognosis in p16-negative cervical cancer patients." (PMID 31980713, 2020). "Previous studies found a correlation between galectin-3 and the development of cervical cancer." (PMID 31980713, 2020). "Recently our study identified EP3 receptor and galectin-3 as prognosticators of cervical cancer." (PMID 31980713, 2020). "This suggests that crosstalk might exist in them, therefore, EP2/EP3/galectin-3 signaling pathway would be analyzed in further in vivo investigations with cervical cancer cell lines (HeLa, CaSki, Siha and C-33A)." (PMID 31980713, 2020). "We found that association of the EP2 receptor with either high galectin-3 or negative EP3 expression cervical cancer patients resulted in better survival in both subgroups, respectively." (PMID 31980713, 2020). "EP2, EP3, and galectin-3 could be targeted for clinical diagnosis or endocrine treatment in cervical cancer patients, which demands future investigations." (PMID 31980713, 2020). "The role of galectin-3 in vascular endothelial growth factor C (VEGF-C)-induced cervical cancer cell invasion has been previously investigated, and silencing of galectin-3 expression with specific siRNA largely impaired VEGF-C-enhanced invasion in cervical carcinoma cell line." (PMID 28355349, 2017). "Information about galectin-3 and galectin-9 expression in cervical cancer is limited." (PMID 26066796, 2015). "EP2 in combination with EP3 or galectin-3 might act as prognostic indicators of cervical cancer." (PMID 31980713, 2020). "Further analysis showed bergenin to be a potent-angiogenic agent by reducing key angiogenic proteins like Galectin 3 and MMP-9 (Matrix Metalloprotease 9) in cervical carcinoma cells." (PMID 38961106, 2024). "Within this study we observed that of EP2 percentage score correlates to galectin-3 with immunohistochemical evaluation, possibly indicating a link between the regulation of EP2 and galectin-3 expression in cervical cancer tumor cells." (PMID 31980713, 2020). "Our group previously found other biomarkers of cervical cancer, such as p16, MDM2, galectin-3, H3K9ac and H3K4me3." (PMID 32488496, 2020).